ENSG00000252989
Gene: Small nucleolar RNA gene on chromosome 3 (100,646,121 to 100,646,197, forward strand). Ensembl gene ENSG00000252989.
Homologues: Paralogues in human: SNORA31B (77% identical), SNORA31 (62% identical).